SOX9 (SRY-box transcription factor 9)
Diseases named in the same sentence as SOX9 in open-access papers (continued):
Sharing a sentence is not in itself a finding about the gene and the disease.
melanoma (continued). "In melanoma cell lines, treatment with PGD2 (176803) increased SOX9 expression and restored retinoic acid sensitivity." (PMID 37020558, 2023). "PITX1 overexpression facilitated SOX9 expression by binding to the RE1 (-592/-588) and RE3 (-520/-504) sites within the SOX9 promoter region, thereby inhibiting melanoma cell proliferation and promoting apoptosis." (PMID 37841446, 2023). "The melanocyte differentiation gene MITF and the proapoptotic factor SOX9 were negatively regulated by GDF6, which blocked melanoma differentiation, inhibited cell death, and promoted tumor growth." (PMID 36253873, 2022). "Intriguingly, another study showed that SOX9 and SOX10 are functionally antagonistic regulators of postnatal melanocyte and melanoma development." (PMID 34526609, 2021). "SOX9 is expressed in postnatal melanocytes and can induce expression of SOX10 melanocyte target genes in B16 melanoma cells." (PMID 33424631, 2020). "Another study showed that SOX9 and SOX10 play antagonistic functions in melanoma cells as demonstrated by upregulation of SOX9 expression, which contributed to the pro-apoptotic response induced by SOX10 loss-of-function." (PMID 30642390, 2019). "Immunofluorescence, TCGA database and qPCR were used to analyze the correlation between the expression patterns and levels of SOX9, SOX10 and NEDD9 in melanoma patient samples." (PMID 30642390, 2019). "AlamarBlue, transwell invasion and colony formation assays in melanoma cell lines were conducted to investigate the epistatic relationship between SOX10 and NEDD9, as well as the effects of graded SOX9 expression levels." (PMID 30642390, 2019). "In agreement with this notion, transcription factors SOX9 and SOX10 play important roles in neural crest specification and migration but are also involved in melanoma development." (PMID 30642390, 2019). "Here we focus on the transcription factor SOX9, and show that it influences CEACAM1 expression and immune resistance in melanoma cells." (PMID 26885752, 2016). "In this study we investigate the role of SOX9 in regulating CEACAM1 expression and thereby immune resistance in melanoma cells." (PMID 26885752, 2016). "SOX9 and CEACAM1 mRNA levels were evaluated in 24 melanoma cell cultures to test for a possible correlation." (PMID 26885752, 2016). "In this study, we examine the role of transcription factor SOX9 in the regulation of CEACAM1 expression and immune resistance in melanoma cells." (PMID 26885752, 2016). "To further investigate the specificity of anti-SOX9 antibodies, we performed SOX10 knockdown in human melanoma cell lines in vitro and analyzed SOX10 and SOX9 expression using Western blot analysis." (PMID 25629959, 2015). "Among these genes MITF, WNT/beta Catenin, SOX9, SOX2, PAX3, RANK/RANKL are important in melanocyte differentiation and melanoma." (PMID 25612317, 2015). "We therefore endeavoured to formally demonstrate the implication of CREB, SOX9 and SOX10 factors in meloe promoter activity, first by evaluating their expression in melanoma cells." (PMID 24086527, 2013). "ChIP experiments further formally demonstrated the in vivo binding of SOX9, SOX10 and P-CREB on meloe promoter region in melanomas." (PMID 24086527, 2013). "Among them, those participating in melanocyte differentiation and melanogenesis belong to the SOX-E group, including SOX9 and SOX10, both expressed in established melanoma cell lines." (PMID 24086527, 2013). "In melanoma, the proliferative state is thought to be characterized by high expression of SOX10, whereas the mesenchymal, invasive state is characterized by high expression of SOX9." (PMID 40879132, 2025). "The mRNA expression of Sox9 did not change significantly in melanoma cell lines but decreased in melanocytes." (PMID 41465475, 2025). "Similarly, in melanoma PITX1 can bind to RE1 (-592/-588) and RE3 (-520/-504) within the SOX9 promoter region, promoting SOX9 expression, apoptosis and inhibiting melanoma cell proliferation." (PMID 40342824, 2025).
melanoma (continued). "Thus, the PACAP-induced increase in p-SOX9, together with the reduction in SOX10, favours a transcriptional environment that shifts melanoma cells toward a more differentiated and less invasive state." (PMID 41465475, 2025). "Knockdown experiments revealed that suppression of PITX1 resulted in decreased SOX9 expression, whereas overexpression of PITX1 led to activated and increased SOX9 expression, inhibiting the growth and proliferation of melanoma by suppressing SOX10 and SAMMSON." (PMID 37841446, 2023). "In addition, the genes EBI3, GH1, SOX9, RET, and SPRY2 are also good candidates for HH-GLI targets but exhibited a less uniform expression pattern in these melanoma cell lines." (PMID 36139698, 2022). "SOX9 and SOX10 show antagonistic functions in the regulation of melanoma phenotype." (PMID 35406721, 2022). "Interestingly, PITX1 binds to the SOX9 promoter region as a positive regulatory transcription factor; PITX1 mRNA expression levels were positively correlated with SOX9 expression, and negatively correlated with SOX10 expression in melanoma tissues." (PMID 34526609, 2021). "Intriguingly, increased SOX9 expression by PITX1 eventually leads to suppressive effects on cell proliferation and induction of apoptosis via downregulation of SOX10 and SAMMSON, which play an oncogenic role in melanoma." (PMID 34526609, 2021). "Immunofluorescence staining showed that NEDD9 was localized in the cytoplasm and co-expressed with most, if not all, of SOX10+ pigmented nevus and primary melanomas, whereas SOX9 was barely detectable." (PMID 30642390, 2019). "Although both SOX9 and SOX10 exhibit differential expression patterns in melanomas, whether they share the same or distinct transcriptional targets in mediating the oncogenic events is not known." (PMID 30642390, 2019). "Without analyzing single-mismatch alignments of guides targeting SOX9, one would have erroneously concluded that most of the melanoma cell lines in the Achilles dataset have a SOX9, rather than a SOX10, dependency." (PMID 30683138, 2019). "Indeed, SOX9 OE at the highest titer (200 μL) in both SOX10 KD A375M and WM266–4 melanoma cells significantly restored the levels of NEDD9 mRNA and protein expression of both parental and phosphorylated forms compared to SOX10 KD alone." (PMID 30642390, 2019). "In contrast, SOX9 expression was significantly upregulated in SOX10 KD, consistent with previous observations that SOX10 normally suppressed SOX9 expression which otherwise would have elicited a pro-apoptotic response in melanoma cells." (PMID 30642390, 2019). "Co-immunoprecipitation studies show that SOX9 and Sp1 physically interact in melanoma cells, while silencing of SOX9 down-regulates ETS1, but not Sp1, in the same cells." (PMID 26885752, 2016). "Shakova and coworkers observed an efficient reduction of tumorigenesis in animal models and in human melanoma cells when reducing SOX10 expression levels and for this anti-tumoric effect they found SOX9 to be required as a functional antagonistic regulator of SOX10." (PMID 26927636, 2016). "Of note, in human melanoma cell lines in vitro, all antibodies tested but sc-20095 not only recognized SOX9, but also a protein of the molecular weight of SOX10 and detected by a SOX10-specific antibody." (PMID 25629959, 2015). "Furthermore, upon experimental elevation of SOX9 levels, SOX10 activity is suppressed, revealing an antagonistic relationship between SOX9 and SOX10 in melanoma initiation." (PMID 25629959, 2015). "To address this hypothesis, we overexpressed SOX9 in human M010817 melanoma cells in vitro and compared the gene expression profile of these cells with that of SOX10 knock-down melanoma cells, using the parental M010817 cell line as control." (PMID 25629959, 2015). "Unlike SOX10, SOX9 is not required for normal melanocyte stem cell function, the formation of hyperplastic lesions, and melanoma initiation." (PMID 25629959, 2015).
melanoma (continued). "To examine the effects of SOX9 in vivo, we utilized the B16F1 mouse melanoma cells which do not express sox9 and are known not to metastasis in a tail vein injection assay." (PMID 25885555, 2015). "In contrast, murine Sox9 appeared not to be expressed in melanocytic cells of the normal skin, nevi, and primary melanoma, while it was readily detectable in epithelial cells in accordance with previous reports." (PMID 25629959, 2015). "Protein expression of SOX9 was detected in all invasive phenotype melanoma cell lysates, but little to no expression of SOX9 was seen in the proliferative phenotype melanoma cell lysates." (PMID 25885555, 2015). "SOX9 protein was strongly present in melanoma cells, and weakly detected in colon cancer and mesothelioma cell lines whereas SOX10 expression was restricted to melanoma cell lines." (PMID 24086527, 2013). "It has also been reported in the literature that reduced expression of SOX9 in SKCM and overexpression of SOX9 in melanoma cell lines suppressed tumorigenesis in both mouse and human in vitro models, indicating that SOX9 may be a tumor suppressor gene in both cancer types." (PMID 37020558, 2023). "However, SOX9 expression was weak or negative in melanoma specimens but positive in normal skin, and upregulation of SOX9 expression significantly inhibited tumorigenesis in both melanoma-bearing mice and human melanoma ex vivo models." (PMID 37020558, 2023). "Active SOX9-binding dimer motifs in regulatory regions of target genes are cell-type specific: SOX9 dimerizes on palindromic composite DNA motifs separated by 3–5 nucleotides in melanoma cells and chondrocytes, whereas no enrichment of palindromic sequences is observed in hair follicle stem cells." (PMID 36114905, 2022). "First, high level and activity of AhR mediates the invasive/dedifferentiated phenotype of melanoma through the direct regulation of the expression of many genes involved in invasion (COL1A1, COL6A1, COL6A2, CYR61, STC2...) and dedifferentiation phenotypes (CCL2, NTM, NUAK2, SOX9, ABCG2...)." (PMID 36305167, 2022). "Finally, both SOX9 and SOX10 have roles in the etiology of melanoma." (PMID 33424631, 2020). "SOX10 has been shown to be a crucial regulator in melanomagenesis but previous conflicting reports have not clearly defined whether SOX9 functions as a suppressor or an inducer in melanoma progression." (PMID 30642390, 2019). "Conversely, opposite phenomenon was observed when SOX9 expression was further elevated to a range of high SOX9 expression levels in metastatic melanoma specimens, and that high levels of SOX9 can restore melanoma progression in the absence of SOX10 both in vitro and in vivo." (PMID 30642390, 2019). "By looking at the relationship between the CERES score for SOX9 and its expression, we noticed several cell lines with very low expression of SOX9 that exhibit a clear and contradictory dependency on SOX9 (CERES score close to − 1); most of these cell lines are melanoma cell lines." (PMID 30683138, 2019). "In contrast, SOX9 expression began to express in a subset of NEDD9+ melanoma cells, which had metastasized to the small intestine and another subset of NEDD9+ cells exhibited SOX10 expression, whereas we detected co-expression of SOX10, SOX9, and NEDD9 in another patient with intestinal melanomas." (PMID 30642390, 2019). "On the contrary, other studies revealed that SOX9 was highly expressed in metastatic melanoma patient samples and contributed to melanoma invasion, suggesting that SOX9 is a negative prognostic factor in advanced melanoma." (PMID 30642390, 2019). "In addition, NEDD9, SOX9, and SOX10 have been shown to be crucial for human melanoma metastasis." (PMID 30642390, 2019). "This is likely because SOX9 acting upstream of NEDD9 can regulate multiple downstream targets as previously demonstrated by RNAseq analysis, which revealed a few novel candidates that could potentially drive the invasive melanoma phenotype." (PMID 30642390, 2019).
melanoma (continued). "Conversely, SOX9 is expressed in normal human melanocytes but its expression gradually downregulates as melanocytic cells progress from nevi to primary melanoma and are completely absent in the metastatic state, suggesting its negative role in melanoma progression." (PMID 30642390, 2019). "Altogether, our results demonstrate that SOX10 or high level of SOX9 expression could regulate focal adhesion dynamics and Rho GTPase signaling, partly through modulation of NEDD9 activity to promote mesenchymal migration of melanoma." (PMID 30642390, 2019). "To further determine whether SOX10 and/or SOX9 can regulate NEDD9 expression through transactivating its promoter, we performed luciferase reporter assay driven by the NEDD9 promoter (~ 1 kb) in both A375M and WM266–4 melanoma cell lines." (PMID 30642390, 2019). "To gain insight into the possible interplay between SOX10 and SOX9 during tumor progression, we quantified the expression levels of SOX10 and SOX9 in normal human melanocytes, in cells from giant congenital naevi, and in a melanoma cell line (M010817;) using quantitative RT-PCR analysis." (PMID 25629959, 2015). "To confirm the downregulation of SOX10 upon SOX9 overexpression observed in microarray analysis also on the protein level, we performed Western blot analysis and observed a pronounced downregulation of SOX10 protein upon SOX9 overexpression in human melanoma cell lines." (PMID 25629959, 2015). "TMEM158 is upregulated by SOX9 but no clear role has been established for the gene in melanoma." (PMID 25885555, 2015). "Moreover, our data do not exclude a role of SOX9 at later stages of melanoma disease progression, in particular during metastasis formation by invasive cells." (PMID 25629959, 2015). "Thus, SOX10 but not SOX9 is prominently expressed in normal human melanocytes, human giant congenital naevi, and primary melanoma." (PMID 25629959, 2015). "In this research, we aimed to resolve contradictory results whether SOX9 plays a positive or negative role in melanoma progression and determine whether SOX9 and its closely related member SOX10 share the same or distinct targets in mediating their functions in melanoma." (PMID 30642390, 2019). "Importantly, the upregulated levels of SOX9 expression in SOX10 KD A375 (1.5 to 2.6 fold) and WM266–4 (1.5 to 3.4 fold) are clinical relevant as they fall within the range of SOX9 expression levels detected in some specimens of primary melanoma (1.3 to 3.7 fold)." (PMID 30642390, 2019). "Indeed, while we could attribute a SOX10 high/SOX9 low signature to proliferative human melanoma cell lines and to all human and murine melanoma tissues analyzed, several human melanoma cell lines reported to display invasive features exhibited SOX10 low/SOX9 high expression." (PMID 25629959, 2015). "There were no clinical metrics that could distinguish SOX9 high or low in primary melanoma." (PMID 25885555, 2015). "We observed a substantial decrease in viability for both melanoma cell lines after SOX10 knockdown with three of three tested siRNAs, while SOX9 knockdown did not lead to an apparent decrease in cell viability." (PMID 30683138, 2019). "Overall, there results confirm specificity of the SOX9 and SOX10 siRNAs, and that SOX10 knockdown, unlike SOX9 knockdown, reduces cell viability in melanoma cell lines." (PMID 30683138, 2019). "We propose that this is not the case in melanocytic cells and that SOX9, unlike SOX10, is neither required for normal melanocyte stem cell homeostasis nor for formation of congenital nevi and primary melanoma." (PMID 25629959, 2015). "Thin primary melanomas (such as MM28, Breslow = 0.8 mm) or thick primitive melanomas (such as MM25, Breslow = 16 mm) displayed a proliferative/differentiated ZEB2+ MITF+ SOX10+ phenotype with no or low ZEB1, SOX9 and NGFR expression." (PMID 38519642, 2024). "Whether SOX9 and/or SOX10 exhibit a similar regulatory relationship with NEDD9 in melanoma has not yet been examined." (PMID 30642390, 2019).
melanoma (continued). "Moreover, there was no strict correlation between the patterns of SOX9, SOX10, and NEDD9 expression and distribution of pigmented melanomas in all examined stages." (PMID 30642390, 2019). "Since in vivo tumors contain a mix of melanoma and nonmelanoma cells, we also asked whether any correlation with PAX3 or MITF was observed in 53 melanoma cell lines grouped according to four different melanoma phenotypes distinguished by SOX10, SOX9, and MITF expression." (PMID 34819350, 2021).